CBS (cystathionine beta-synthase)
Diseases named in the same sentence as CBS in open-access papers (continued):
Sharing a sentence is not in itself a finding about the gene and the disease.
lung carcinoma (continued). "This cascade induces hypermethylation and high expression of CBS, consequently triggering cysteine production and maintaining antioxidative homeostasis, which is essential for the survival of KRAS-driven lung cancer cells." (PMID 40885716, 2025). "In non‐small cell lung cancer (NSCLC) cell lines A549 and 95D, the expressions of CBS and CSE were significantly up‐regulated." (PMID 36929586, 2023). "Given DDX3X role as a crucial RNA-binding protein governing various aspects of gene expression, our study in KRAS-driven lung cancer cells revealed that DDX3X influences CBS translation without affecting transcription or mRNA stability." (PMID 40885716, 2025). "CBS (rs2850146) and MTRR (rs3776467) SNPs may, in combination with high folic acid levels, protect against lung cancer." (PMID 25988111, 2014). "Conversely, the overexpression of either CBS or GCLC in A549 cells led to accelerated cell proliferation and diminished Fe2+ and lipid peroxidation levels, underscoring the vital roles of these enzymes in modulating antioxidant homeostasis and lung cancer progression." (PMID 40885716, 2025).
prostate carcinoma (14 papers, 2016 to 2025). A carcinoma that arises from epithelial cells of the prostate gland. "Sulphoraphane has been postulated to exert anticancer property, to suppress the proliferation of prostate cancer cells and to enhance the expression of CBS and CSE." (PMID 32085474, 2020). "CSE expression is also lower in antiandrogen-resistant prostate cancer cells in comparison with their parental LNCaP cells, whereas the expression of CBS is similar between these two types of cells." (PMID 27019751, 2016). "Furthermore, we searched the protein levels of CBS in PCa cell lines and tissues by Western blot, and significantly increased expression of CBS in prostate cancer was observed." (PMID 40629411, 2025). "Targeting CBS effectively hinders prostate cancer growth and induces tumor cell death." (PMID 39062461, 2024). "The expression of CSE and CBS is also reduced in prostatic cancer cell lines." (PMID 35684331, 2022). "Several studies suggest that H2S may regulate cancer cell growth and tumor progression and that the expression of CSE and CBS is reduced in antiandrogen-resistant prostate cancer cells." (PMID 32085474, 2020). "Hence, prostate cancer tissues may upregulate CBS expression to compensate and restore metabolic balance, explaining the observed increase in CBS in these tissues." (PMID 40629411, 2025). "Moreover, simultaneous inhibition of HSF1 and CBS significantly enhances the suppression of prostate cancer cell proliferation and reduces transsulfuration pathway metabolites, underscoring a potent strategy for tackling prostate cancer progression." (PMID 39062461, 2024). "An androgen-dependent prostate cancer cell line (LNCaP) demonstrated noticeable degrees of CSE and CBS expression." (PMID 35684331, 2022). "Endogenous H2S and all three enzymes (CBS, CSE, and 3-MPST) have been demonstrated in healthy and prostate cancer." (PMID 31781328, 2019). "The protein levels of CBS and CSE are greatest in the androgen-dependent prostate cancer cell LNCaP in comparison with all other cells." (PMID 27019751, 2016). "Similarly, in many other prostatic cancer cell lines, both CBS and CSE expression and reduced expression of CBS and CSE were observed." (PMID 35684331, 2022). "In addition, both CBS and CSE are present in mouse prostate cancers, unrelated to androgen dependency, and in vitro work showed that CSE is the main contributor to H2S production in prostate cancer cell lines (PC-3)." (PMID 31781328, 2019). "However, in another study, they could not detect the expression of 3-MPST in both normal and cancerous prostate tissues, but they showed that CSE was significantly downregulated in prostate cancer, whereas CBS was not changed in each sample." (PMID 31781328, 2019). "CBS expression is low or absent in the normal prostate peripheral zone epithelial cell line RWPE-1, while CBS expression is high in the androgen-dependent prostate cancer cell line LNCaP." (PMID 35684331, 2022).
ischemic stroke (13 papers, 2015 to 2025). A stroke disorder caused by obstruction of blood flow to the brain, due to thrombotic (local blood clot formation) or embolic (due to a blood clot or other material traveling from another site) event. "The aim of the study was to assess the impact of vitamin B therapy, MS and CBS gene polymorphisms on homocysteine levels, and cardiovascular events in ischemic stroke patients." (PMID 40718281, 2025). "In the view of these, we finally revealed that the new mechanism of ischemic stroke treatment of SPRC is associated with the CBS/H2S/CD24/Iκ‐Bα/NF‐κB inflammatory pathway and CBS/H2S/CD24/Src/Fak/Pyk2 migration pathway." (PMID 39953809, 2025). "Recent evidence from proteomic studies using label-free mass spectrometry suggests that ischemic strokes in CBS-deficient patients are related to ischemic strokes in the general population." (PMID 39859460, 2025). "Little is known regarding the mechanisms leading to the onset of ischemic stroke in CBS-deficient patients." (PMID 39859460, 2025). "The authors concluded that common mechanisms exist between individuals with CBS deficiency and ischemic stroke, particularly cardioembolic stroke, as a result of proteome alterations in molecular networks possessing strong interactions with NFκB." (PMID 33212887, 2020). "There were significant overlaps between proteins affected by CBS deficiency and ischemic stroke, particularly the cardioembolic subtype, similar to protein overlaps between ischemic stroke subtypes." (PMID 31242583, 2019). "We found that many of the proteins affected by CBS deficiency were also affected in ischemic stroke patients." (PMID 31242583, 2019). "Our results suggest that CBS deficiency and ischemic stroke, particuraly the cardioembolic stroke subtype, share similar molecular mechanisms." (PMID 31242583, 2019). "Top molecular pathways affected by CBS deficiency and ischemic stroke subtypes included acute phase response signaling and coagulation system." (PMID 31242583, 2019). "Reduced levels of SERPINC1 that we found in the CBS-deficient patients in the present study were also observed in Han Chinese ischemic stroke patients." (PMID 31242583, 2019). "Reduced AFM and TTR, which we found in the cardioembolic vs. large-vessel stroke comparison and in the CBS deficiency, were also observed in Han Chinese ischemic stroke patients." (PMID 31242583, 2019). "For these reasons, the present work was undertaken to ascertain proteomic signatures associated with CBS deficiency and ischemic stroke subtypes." (PMID 31242583, 2019). "We accomplished this aim by using label-free mass spectrometry and bioinformatic analyses to study changes in serum proteomes associated with CBS deficiency and ischemic stroke subtypes and to identify molecular pathways and networks involved." (PMID 31242583, 2019). "Comparisons of proteomes between CBS deficiency, on the one hand, and ischemic stroke subtypes, on the other, indicate that sevaral proteins and molecular pathways are shared between these pathologies." (PMID 31242583, 2019). "Although little is known regarding the mechanisms leading to the onset of ischemic stroke in CBS-deficient individuals, 32% of those patients suffer thromboembolic stroke." (PMID 31242583, 2019). "In conclusion, our study revealed previously unanticipated similarties between proteomic signatures of CBS deficiency and ischemic stroke subtypes, suggesting that similar mechanisms are involved in both pathologies." (PMID 31242583, 2019). "Only four out of 10 CBS-deficient patients suffered ischemic strokes, which ocurred long before their participation in the present study." (PMID 31242583, 2019). "Our study also highlights subtle molecular differences between CBS deficiency and ischemic stroke subtupes." (PMID 31242583, 2019). "Secondky, CBS-deficient patients (37.3 ± 7.3 years) were much younger than ischemic stroke patients (67.5 ± 12.4 years)." (PMID 31242583, 2019).
ischemic stroke (continued). "The treatment of SPRC on ischemic stroke is associated with CD24 via CBS/H2S pathway." (PMID 39953809, 2025). "IPA identified similar sets of biological networks for CBS deficiency and ischemic stroke subtypes." (PMID 31242583, 2019). "Because thromboembolism involves the brain vasculature in these patients, we hypothesize that CBS deficiency and ischemic stroke have similar molecular phenotypes." (PMID 31242583, 2019). "Similarly, KLKB1, which was reduced in the cardioembolic vs. large-vessel stroke and in the CBS-deficient patients, was found to be reduced in Han Chinese ischemic stroke patients." (PMID 31242583, 2019). "Thus, CBS deficiency causes chronic dysregulation of the proteostasis in the circulation, which affects the blood-clotting system and makes the CBS-deficient patients prone to ischemic strokes." (PMID 31242583, 2019). "Following the found association of CBS deficiency and vascular thromboembolism, researchers sought to compare proteome alterations in CBS-deficient individuals to those with various subtypes of ischemic stroke (e.g., cardioembolic, lacunar, and large-vessel stroke)." (PMID 33212887, 2020). "We used label-free mass spectrometry for quantification of changes in serum proteomes in CBS-deficient patients (n = 10) and gender/age-matched unaffected controls (n = 14), as well as in patients with cardioembolic (n = 17), large-vessel (n = 26), or lacunar (n = 25) ischemic stroke subtype." (PMID 31242583, 2019). "Thus, CBS deficiency has two effects: Hcy-related, involving a set of 18 specific proteins, and Hcy-independent, involving a set of 22 other proteins that were also affected in patients with different ischemic stroke subtypes, in whom Hcy and anti-N-Hcy-protein autoantibody levels were not elevated." (PMID 39859460, 2025). "An analysis of proteins and biological pathways affected by CBS deficiency and ischemic stroke subtypes was not previously reported." (PMID 31242583, 2019). "Several additional experiments come to the conclusion that either CBS or its downstream products may in fact be negative contributors for risk of ischemic stroke." (PMID 33212887, 2020). "For example, some of the differentiation proteins, such as SERPINA3 and CRP involved in inflammatory/acute-phase response, as well as FGA and PLG involved in blood coagulation, were associated with the cardioembolic, large-vessel, and lacunar ischemic stroke subtypes, but not with CBS deficiency." (PMID 31242583, 2019). "Therefore, the present results may support the idea that CBS is a viable therapeutic target, and CBS inhibition may hold promise as a treatment of ischemic stroke." (PMID 25873304, 2015). "In ischemic stroke models, SPRC upregulated cluster of differentiation 24 (CD24) expression via the CBS/H2S signaling pathway, suppressing NF-κB and enhancing src/focal adhesion kinase/proline-rich tyrosine kinase 2 (Src/Fak/Pyk2)-dependent microglial migration." (PMID 41465271, 2025). "Thus, our present findings, in conjunction with the mouse Orm2 study, suggest that the high upregulation of Orm2 would protect Cbs−/− mice from ischemic stroke, and that this protective response is not induced in CBS−/− patients." (PMID 32612202, 2020).
Cognitive impairment (11 papers, 2018 to 2024). Abnormal cognition is characterized by deficits in thinking, reasoning, or remembering. "CBS dysfunction results in increased homocysteine levels, which are linked to cardiovascular illnesses and cognitive deficits." (PMID 39204195, 2024). "Clinical studies have also confirmed that CBS-deficient patients experience a wide range of destructive phenotypes, including cognitive impairment, premature atherosclerosis, dislocated lenses, thrombosis, vascular complications and osteoporosis." (PMID 30323246, 2018). "CBS plays a crucial part in the metabolism of homocysteine, and any dysfunction in this process can lead to cardiovascular diseases and cognitive impairments." (PMID 39204195, 2024). "Studies showed that the decreased activity of CBS mediates homocysteine- and formaldehyde-induced cognitive deficits." (PMID 30733697, 2019). "Taken together, these data provide further understanding into the regulation of CBS and in particular into the genetic relationship between DYRK1A and CBS through the Akt/GSK3β and NF-κB pathways, which should help develop more effective therapies to reduce cognitive deficits in people with DS." (PMID 36711154, 2022). "Injection of Aβ1–42 into the hippocampi of rats induced cognitive impairment and reduction in H2S levels and expression of endogenous CBS and 3-MST and intraperitoneal injection of the H2S donor, NaSH, ameliorated cognitive deficits as well as neuroinflammation." (PMID 33796019, 2021).
gastric cancer (11 papers, 2012 to 2025). A primary or metastatic malignant neoplasm involving the stomach. "Previous studies have demonstrated CBS deficiency in human gastric cancer cells with hyper-methylation at the CBS promoter region, implicating loss of CBS through epigenetic regulation in gastric cancer." (PMID 35758651, 2022). "Given the GES-1 cells express high levels of CBS as well as activated AKT signaling comparable to some of gastric cancer cell lines, we used this cell line to interrogate the role of CBS loss in the initiation of gastric cancer." (PMID 35758651, 2022). "Loss of cystathionine-β-synthase (CBS) synergizes with PI3K/AKT pathway to promote gastric cancer pathogenesis." (PMID 35758651, 2022). "CBS genetic alterations were found in 18 of 441 gastric cancers with 12 cases cooccurring with mutations in PI3K/AKT/mTORC1 pathway." (PMID 35758651, 2022). "To further test if CBS loss cooperates with PI3K/AKT/mTORC1 hyperactivation in gastric cancer oncogenesis, we transduced myrAKT1 and CBS shRNA into GES-1 cells and tested their ability to form colonies in soft agar." (PMID 35758651, 2022). "To gain insight into this, we further characterized the expression level of CBS in gastric cancer tissue samples and cells and sought to define the functional significance of CBS loss in the context of activated PI3K/AKT signaling-driven gastric cancer development." (PMID 35758651, 2022). "The downregulation of CBS expression inhibits ferroptosis in gastric cancer (GC) cells by promoting the degradation of ACSL4." (PMID 40271153, 2025). "Further validation in gastric cancer cell lines reveals that knockdown of CBS results in excessive activation of PI3K/Akt signaling pathway and promotes oncogenic transformation." (PMID 38448410, 2024). "A novel association between CBS epimutations and the CIMP subtype in gastric cancer was discovered, with in vitro models of CBS deficiency resulting in abnormal DNA methylation and inflammatory response." (PMID 37483514, 2023). "(G) Correlation of CBS mRNA expression with CBS DNA methylation in 34 gastric cancer cell lines based on the data retrieved from the Cancer Cell Line Encyclopedia." (PMID 35758651, 2022). "We demonstrated suppression of CBS expression in primary gastric tumor tissues and a panel of human gastric cancer cell lines through epigenetic silencing." (PMID 35758651, 2022). "Cystathionine-β-synthase (CBS) expression is suppressed in tumor tissues and human cell lines of gastric cancer." (PMID 35758651, 2022). "Compared to gastric epithelial cells, CBS expression was markedly decreased in all gastric cancer cell lines while elevated AKT activity, as indicated by increase of AKT phosphorylation, was observed in AGS, Hs746T, KATO III gastric cancer cell lines." (PMID 35758651, 2022). "The aims of the present study were to detect CSE and CBS proteins in human gastric cancer and determine the effect of exogenous NaHS on the proliferation of gastric cancer cells." (PMID 26078811, 2015). "We found that both CSE and CBS proteins were expressed in human gastric cancer cells and upregulated in human gastric carcinoma mucosa compared with those in noncancerous gastric samples." (PMID 26078811, 2015). "To this end, we studied expression of CSE and CBS in human gastric cancer samples and explored the effects of exogenous H2S donor NaHS on the phenotypic functions of gastric cancer SGC7901 cells." (PMID 26078811, 2015). "A novel finding from this study is that the folate metabolism enzyme CBS mRNA levels are frequently downregulated through CpG methylation of the CBS gene in gastric cancer and CRC, suggesting that CBS functions as a tumor suppressor gene." (PMID 23152928, 2012). "Semiquantitative RT-PCR showed that CBS expression was decreased or silenced in 56.3% (9/16) of gastric cancer and 75.0% (3/4) of CRC cell lines." (PMID 23152928, 2012).